ATM (ATM serine/threonine kinase)
Diseases named in the same sentence as ATM in open-access papers (continued):
Sharing a sentence is not in itself a finding about the gene and the disease.
breast cancer (continued). "The current panel of genes with strong evidence for use in clinical practice include PALB2, CHEK2, ATM, RAD51C and RAD51D with additional genes such as BARD1 (breast cancer) and BRIP1 (ovarian cancer) continuing to emerge." (PMID 39107016, 2024). "BOADICEA V5’s newest version includes the effects of pathogenic variants (PVs), not restricted to BRCA1 and BRCA2 genes but also in PALB2, CHEK2, ATM, and BARD1 for the breast cancer model and RAD51D, RAD51C, and BRIP1 for the ovarian cancer model." (PMID 39590369, 2024). "Concerning breast cancer, the 1CM-involved genes are highly overlapped in the alterations derived from the breast cancer network, which uses BRCA1, BRCA2, CHEK2, and ATM as reference genes for the disease." (PMID 39125744, 2024). "Functional enrichment on the 10 miRs revealed their general involvement in cancer and breast cancer pathways, PI3K—Akt signaling pathway as well as the ATM-dependent DNA damage response (Wikipathways)." (PMID 37491482, 2023). "Other clinical responders whose tumors had biallelic LOF included two patients with CRPC (somatic ATM and CDK12 alterations) and one with germline BRCA1-altered breast cancer." (PMID 37277454, 2023). "In another study, Timosaponin AIII was found to induce the breast cancer MDA-MA-231 and MCF7 cells arrested at G2/M phase due to ATM/Chk2 activation." (PMID 37047251, 2023). "Poly (ADP‐ribose) polymerase (PARP) inhibitors of BRCA1/2 and ATM, such as Olaparib, have been approved by US FDA for breast cancer and ovarian cancer treatment." (PMID 36653904, 2023). "At least three genes from this list were involved in the formation of carcinomas, including breast carcinoma (CASP8, HSPA4, BCL2L11), prostate carcinoma (BCL2, CASP8, BCL2L11, ATM), and chronic lymphocytic leukemia (BCL2, CASP8, FAS, BCL2L11, BAK1)." (PMID 37298337, 2023). "For breast cancer, several genes such as BRCA1, BRCA2, PALB2, ATM, and CHEK2 act as high- to moderate-penetrance cancer susceptibility genes." (PMID 35853889, 2022). "Another genetic variation associated with intermediate dangers of breast cancer and a 20%–40% lifetime chance of getting breast cancer includes the CHEK2, ATM, and PALB2 genes involved in the DNA repair process." (PMID 35762299, 2022). "Taken together, these results demonstrate that hypoxia induces TRIM28- and KU70/86-dependent, but ATM- and DNA damage-independent, activation of DNA-PKcs, which is required for HIF target gene expression in human breast cancer cells." (PMID 35031618, 2022). "The promoters of several known tumor suppressor genes (e.g., ATM, BRCA1, and PALB2) were all hypermethylated in WTC exposed breast cancer cases compared to the unexposed group." (PMID 35564499, 2022). "In breast cancer, ATM activity reduced recurrence time in patients with invasive HER2‐positive; moreover ATM was found to be involved in HER2 tumour progression." (PMID 36056635, 2022). "Taken together, we identified a synthetic lethal interaction between EZH2 and ATM and propose this synergistic interaction as a novel molecular combination for the treatment of BRCA1-mutant breast cancer." (PMID 35715861, 2022). "A quarter of ATM-related breast cancer and approximately one-third (30%) of CHEK2-related breast cancers were in situ carcinomas." (PMID 35008774, 2021).
breast cancer (continued). "ATM also increases the expression of ATG4C at the mRNA and protein levels, promoting autophagy in breast cancer stem cells." (PMID 34070860, 2021). "Recently, it has been shown that ATM knockdown sensitized breast cancer cells to irradiation, and reduced phosphorylation of γ-H2AX, highlighting a strong relationship between ATM, DNA repair pathway and radioresistance." (PMID 34268251, 2021). "Activation of the TGFβ pathway was shown to result in reduced expression of ATM, BRCA1 and BRCA2 in BRCA-proficient breast cancer cells, and of RAD51 in lung epithelial cells -resulting in suppression of DNA damage repair." (PMID 34871431, 2021). "Previous studies analyzing the ATM gene in European women (42,671 cases and 42,164 controls) found an association between ATM mutations (c.7271 T > G) and overall breast cancer risk; however, a specific association with TNBC could not be determined because the tumors were not stratified by subtype." (PMID 34198652, 2021). "Mutations in BRCA1/2 genes, especially germline variations, along with other Fanconi anaemia (FA) pathway genes (such as NBN, RAD54L, ATM), are prototypic molecular alterations that confer HRD in breast cancer." (PMID 34465315, 2021). "Three women had bilateral breast cancer with VUS in APC, ATM, and BRCA2, 2 of whom were diagnosed before the age of 50 years." (PMID 33646313, 2021). "EIF3E, another 8q-protein in the RRM2B network, interacts with ATM and BRCA1 for the execution of DNA damage response and EIF3E alterations have been previously observed in breast cancer." (PMID 33868369, 2021). "A recent study showed that KIFC1 phosphorylation by ATM and ATR kinase is involved in drug resistance in breast cancer." (PMID 34768355, 2021). "Here, we find that TAIII triggered DNA damage through activating the ATM/Chk2 and p38 MAPK signaling, leading to G2/M arrest and apoptosis in breast cancer." (PMID 33628174, 2020). "Our results showed that TAIII activated the DDR pathway (ATM/Chk2/Cdc25C) and γ-H2AX quickly, indicating that TAIII induces DNA damage in breast cancer cells." (PMID 33628174, 2020). "Interestingly, ATM c.2289T>C (p.F763L), along with two other variants currently classified as likely benign, BRCA2 c.2926_2927delinsAT (p.S976I) and RAD51D c.251T>A (p.L84H), were determined to be associated with African American breast cancer risk when compared to ethnic-specific controls." (PMID 32866190, 2020). "More specifically, ATM knockdown via siRNA oligos in breast cancer SK-BR3 and MDA-MB231 cells or ATM knockout in mouse embryonic fibroblasts (MEFs) extended TOP2β protein half-life upon VM-26 treatment." (PMID 32015321, 2020). "Susceptibility genes with high or moderate penetrance (i.e., BRCA1, BRCA2, PALB2, ATM, and CHEK2) have been identified in 30 to 40% of patients with a family history of breast cancer, but only in 5% of sporadic breast cancer cases." (PMID 33126731, 2020). "Inhibition of ATM increased radiation sensitivity of the isolated CD44+/CD24- cell, which suggests that ATM is a potential target to improve radiation sensitivity in breast cancer therapy." (PMID 33680952, 2020). "Consistently, irradiation therapy in breast cancer cells results in massive miR-205 downregulation, accompanied by upregulation of ZEB1, which can be completely reversed by inhibition of ATM or direct depletion of ZEB1." (PMID 32266287, 2020).
breast cancer (continued). "Our results demonstrate that TAIII activates both ATM and p38 MAPK pathways, then inhibits Cdc25C level, inducing G2/M phase arrest in breast cancer cells." (PMID 33628174, 2020). "In conclusion, we provide strong clinical evidence that ATM signalling and ATR signalling can influence clinicopathological features and survival outcomes in patients with MYC overexpressed breast cancer." (PMID 30746633, 2019). "For example, RALY and SNW1 stimulate exon 2 inclusion in PRMT1, promoting breast cancer invasiveness and CDK12 promote alternative last exon splicing of DNA damage genes ATM and DNAJB6 thereby increasing migration and invasiveness of breast cancer cells." (PMID 31666932, 2019). "Estimates are that about 1.1–1.7% of women with breast cancer have a PV in CHEK2, 1.4–2.1% in BRCA1, 1.6–2.2% in BRCA2, 0.87–1% in ATM, and 0.84–0.87% in PALB2, with other genes less than 1%." (PMID 30832243, 2019). "It should be noted that some genes highly related with breast cancer rank at top but are missed by the NCG4.0 such as the CREBBP, RHOA, HDAC1, ATM and MYC." (PMID 31088372, 2019). "We investigated ATM, ATR and MYC at the transcriptional level [Molecular Taxonomy of Breast Cancer International Consortium cohort (n = 1950)] and at the protein level in the Nottingham series comprising 1650 breast tumours." (PMID 30746633, 2019). "We show that ATM and ATR levels have clinicopathological, predictive and prognostic significance in MYC overexpressed breast cancer." (PMID 30746633, 2019). "It is worth mentioning that, in principle, the role of mutant ATM and CHEK2 as breast cancer genes is still debated." (PMID 29271107, 2018). "Taken together, these studies suggest that activation of ATM can act to drive cytokine expression and increase CTL recruitment to breast cancers." (PMID 29615613, 2018). "Depletion of FOXM1, accompanied by repressed NBS1 expression and reduced ATM activation, can render parental MCF-7 breast cancer cells and MCF-7 epirubicin resistant cells more sensitive to epirubicin-induced cellular senescence." (PMID 29180117, 2018). "Both severe early gastrointestinal toxicities, nausea and vomiting, were dependent on the combination of young age of breast cancer patients and modifications in DNA repair machinery (XRCC1, p.Arg399Glu and ATM, p.Asp1853Asn)." (PMID 29507678, 2018). "Remarkably, we were able to show a correlation between ATM and ATG4C expression in all breast cancer subtypes except for the basal-like one underscoring a clinical impact of our findings." (PMID 28423511, 2017). "Etoposide treatment (a positive control for DNA damage induction) resulted in an elevation in DNA breaks and activation of DNA damage response (DDR) with increased phosphorylation of both ATM and H2AX in three breast cancer cells examined." (PMID 28213701, 2017). "In this study, we described for the first time a mechanism through which ATM regulates autophagy in a fashion independent on HER2, which has crucial implications in breast cancer progression." (PMID 28423511, 2017). "Our data so far demonstrated that miR-302b overexpression in breast cancer cell lines leads to sensitization to cisplatin treatment, by targeting E2F1 and ATM." (PMID 26623722, 2016). "We have demonstrated that miR-302b sensitizes breast cancer cell lines to cisplatin treatment by targeting directly E2F1 and indirectly ATM, reducing cell growth." (PMID 26623722, 2016). "In conclusion our study demonstrates that miR-302b overexpression increases sensitivity of breast cancer cell lines to cisplatin by targeting E2F1 and ATM, further compromising the control of cell-cycle progression and DDR mechanisms." (PMID 26623722, 2016).
breast cancer (continued). "Analysis of publicly available gene expression data showed that exposure of HR-proficient breast cancer cell lines to HSP90i 17-AAG(17-allylamino-17-demethoxygeldanamycin) downregulated HR, ATM and Fanconi Anemia pathways." (PMID 24798692, 2014). "On the other hand, 5 genes were differentially expressed with significant difference between the breast cancer patients and carriers, BRCA1 (p = 0.03), BIRC5 (p = 0.035), CCND2 (p0.034), ATM (p = 0.012) and IGF1R (p = 0.025)." (PMID 25403427, 2014). "For breast cancer, methylation has been noted in genes including BRCA1, p16, E-cadherin, H-cadherin, ATM, CST6, cyclin D2, PTEN, RASSF1A, APC, RARb2, GSTP1, ER, PR, as well as numerous other genes related to multiple pathways relevant for carcinogenesis." (PMID 24368439, 2014). "Wild-type BRCA1/2 breast cancer cells (i.e., MCF-7 and ZR-75-1 lines) were genetically manipulated to downregulate ATM expression then assayed for cytostaticity/cytotoxicity upon treatment with PARP inhibitors, olaparib and iniparib." (PMID 24252502, 2013). "Canonical pathways that were assigned only to day 3 of estrous in the HR group (HR3>HR7) included role of BRCA1 in DNA damage response, ATM signaling, role of CHK proteins in cell cycle checkpoint control, and hereditary breast cancer signaling." (PMID 22952593, 2012). "In male breast cancer, methylation was very rare in BRCA1, CDKN2A, VHL, ATM and CHFR (< 2%) - indicating that methylation of these genes does not seem to play a prominent role in male breast carcinogenesis." (PMID 22765268, 2012). "The genes CD44 (P = 0.050), RARB (P = 0.026), ATM (P = 0.017) and STK11 (P = 0.040) also showed less frequent methylation in male breast cancer." (PMID 22765268, 2012). "The increased expression levels of ATM protein and the phosphorylation level of CHK2 after IR treatment in both breast cancer cell lines were dramatically abolished by the transfection of miR-18a." (PMID 21980462, 2011). "We performed a comprehensive haplotype analysis of the ATM, CHEK2 and ERBB2 genes in a Swedish population-based study, which included 1,579 breast cancer cases and 1,516 controls." (PMID 17132159, 2006). "For ATM, MRE11A, and XRCC4, we compared haplotypes and LD structure between the breast cancer cases and controls." (PMID 16091150, 2005). "The findings of breast cancer risk in mothers, but not other likely mutation carriers, in this and other studies raises questions about the hypothesis of a simple causal relationship with ATM heterozygosity." (PMID 15942625, 2005). "Several circRNAs identified in our analysis, including hsa_circRNA_104310 (ZDHHC4, AUC = 0.80), hsa_circRNA_404935 (ZBTB16, AUC = 0.882), hsa_circRNA_003641 (ATM, AUC = 0.876), and hsa_circRNA_102445 (CARM1, AUC = 0.812), demonstrated strong discriminatory power across breast cancer subtypes." (PMID 41516402, 2026). "Certain circRNAs identified in our analysis demonstrated exceptionally strong discriminatory power across breast cancer subtypes, e.g., hsa_circRNA_104310 (host gene: ZDHHC4), hsa_circRNA_404935 (ZBTB16), hsa_circRNA_003641 (ATM), and hsa_circRNA_102445 (CARM1)." (PMID 41516402, 2026).
breast cancer (continued). "BRCA1/2, ATM, CHEK2, and PALB2 PV carriers do not have breast cancer OR ≥2.0 with many established risk factors." (PMID 40298171, 2025). "Based on these findings, it can be suggested that a mutated ATM, which fails to phosphorylate PTEN, would promote tumorigenesis in this type of cancer (Her2+ breast cancer)." (PMID 40259910, 2025). "Despite ATM’s established significance in breast cancer pathology, no ATM ChIP-seq experiments have been conducted specifically in breast tissue, although such studies have been performed in other tissues." (PMID 41022541, 2025). "ATM and ATR become active and phosphorylate CHK1 and CHK2, which then trigger signaling pathways that result in either cell cycle arrest or apoptosis, thereby impeding the advancement of breast cancer." (PMID 40612872, 2025). "RT-qPCR analysis revealed that ATM mRNA levels were downregulated in p150/p110 KO cells, consistent with previous findings that ADAR1 knockdown breast cancer cells reduces ATM expression without affecting mRNA stability in ZR-75-1." (PMID 41164819, 2025). "The efficacy of ICB in TNBC was improved by ATM inhibition and further augmented by radiation, highlighting the combination of ATM inhibition with ICB and radiation as an effective treatment strategy for breast cancer." (PMID 40825766, 2025). "In summary, postmenopausal carriers of PVs in BRCA1/2, ATM, CHEK2, and PALB2 are unlikely to have substantial (twofold or greater) elevations in the risk of developing breast cancer due to reproductive and lifestyle exposures." (PMID 40298171, 2025). "R/M breast cancer more frequently harbored alterations in BRCA2, ATRX, and ATM (p<0.05)." (PMID 40182039, 2025). "At the pilot sites, PV/LPVs in breast cancer genes were most commonly identified in ATM, BRCA2, and BRCA1, whereas at the non-pilot sites, they were most commonly identified in BRCA2, BRCA1, and PALB2." (PMID 39292401, 2025). "While DVs of ATM, CHEK2, and PALB2 have been linked to breast cancer, the additional risk conferred is not as well understood, especially among individuals with non-European ancestries." (PMID 38760335, 2024). "Two recent large case control studies CARRIERS in the USA3 and BRIDGES mainly in Europe4 identified six additional genes with actionable increased risks of breast cancer with ORs of around twofold to threefold (RAD51C, RAD51D, BARD1, ATM, CHEK2) and one at fourfold to fivefold (PALB2)." (PMID 38609177, 2024). "This level of risk suggests that it is reasonable perform a preventive oophorectomy after menopause in ATM carriers without breast cancer." (PMID 39543654, 2024). "Moreover, c.6115G>A in ATM and c.592+3A>T in CHEK2 were of keen interest identified in families with multiple breast cancer cases and their familial cosegregation with disease has been also confirmed." (PMID 38313678, 2024). "The use of de novo instances is not informative for ATM because breast cancer as a ‘new disease’ cannot be confidently established given the commonness of sporadic breast cancer." (PMID 38854136, 2024). "Moreover, ATM inhibitors help enhance the sensitivity of radiotherapy, and radioresistant breast cancer has enhanced DDR efficiency and increased expression of ATM." (PMID 39334297, 2024). "Furthermore, having a family member with breast cancer can increase the chance of developing prostate cancer due to their genetic makeup (e.g., BRCA1, BRCA2, HOXB13, CHEK2, HOXB13 and ATM)." (PMID 37893854, 2023). "Moreover, TIA was shown to intercept the PI3K/Akt and STAT3 pathways in pancreatic cancer cells, diminish ERK1/2 activity in lung cancer cells, and activate the ATM/Chk2 and p38 MAPK pathways in breast cancer." (PMID 37175205, 2023).